STAT1 (signal transducer and activator of transcription 1)
Diseases named in the same sentence as STAT1 in open-access papers (continued):
Sharing a sentence is not in itself a finding about the gene and the disease.
bladder cancer (13 papers, 2007 to 2025). "PD-L1 might function as a mediator of stage progression in bladder cancer and STAT1-NFAT pathway might associate this function." (PMID 30400941, 2018). "We found that STAT1 was a key gene in a gene regulatory network related to immune phenotypes in bladder cancer." (PMID 33608980, 2021). "STAT1 is considered as an oncogene that promotes cell adhesion, migration, and proliferation in bladder cancer." (PMID 34329197, 2021). "Binding of IL-28A to IL-28AR1 induced the activation of ERK1/2, p38MAPK, and Jak/Stat (Jak2, Jak3, Stat1, Stat3, and Stat5) signaling pathways in bladder cancer cells." (PMID 22962576, 2012). "We have also identified the activation of ERK1/2, p38MAPK, JNK, JAK1, JAK2, JAK3, Stat1, Stat2, and Stat3 in bladder cancer cells." (PMID 22962576, 2012). "OPN, a substrate of Fam20C involved in cell differentiation, was overexpressed in bladder cancer tissues and OPN knockdown could suppress proliferation and invasion of human bladder cancer T24 cell via the JAK1/STAT1 pathway." (PMID 34988120, 2021). "We found that STAT1 was highly expressed in bladder cancer patients." (PMID 33608980, 2021). "In summary, our study suggests that ETS1-mediated overexpression of PLA2G7 can regulate the phosphorylation of STAT1 and STAT3, leading to PD-L1 overexpression and promoting immune evasion in bladder cancer." (PMID 40169540, 2025). "Therefore, the STAT1-PD-L1-NFATc1 pathway was proposed to reveal the immunosuppressive mechanism of PD-L1, which may increase the potential for PD-L1-based antitumor immunotherapy for bladder cancer." (PMID 37138354, 2023). "STAT1 has been reported to exhibit a negative regulatory effect on FOXO1 transcription in pancreatic β cells and bladder cancer." (PMID 29796115, 2018). "Our results from bladder cancer cells indicate that IL-20 induced activation of ERK1/2 and Jak1, Jak2, Jak3, Stat1, Stat2, and Stat5." (PMID 22962576, 2012). "Instead, ectopic expression of SELENBP1 pronouncedly attenuates the phosphorylation of c-Jun and STAT1, both of which are indispensable for SELENBP1-mediated transcriptional induction of p21, thereby resulting in the G0/G1 phase cell cycle arrest in bladder cancer cell." (PMID 31918717, 2020).
endotoxemia (13 papers, 2017 to 2025). "Interestingly and in sharp contrast to the phenotype observed in Casp8ΔIEC mice, additional deletion of Stat1 in these mice (Casp8ΔIECxStat1−/− mice) could protect from severe endotoxemia, body weight loss and lethality." (PMID 34497340, 2022). "MLT also reduces the synthesis of IL-6 and NO during LPS-induced endotoxemia by blocking the NF-κB signaling pathway, thereby blocking its nuclear translocation and DNA binding of the NF-κB p50 subunit and suppressing STAT-1 signaling." (PMID 38203627, 2023). "This study demonstrates that harmine inhibits the expression of inflammatory mediators induced by multiple TLRs in macrophages by modulating the activation of NF-κB p65, JNK, and STAT1, as well as liver inflammation during endotoxemia." (PMID 36556387, 2022). "One study showed that STAT1 knock-out mice were distinctly resistant to LPS-induced endotoxemia and CLP-induced septic shock." (PMID 35197984, 2022). "IFNβ is a known inducer of STAT1 activation, and pulmonary STAT1 activation is known to occur with endotoxemia." (PMID 30319651, 2018). "STAT1 knockout mice are resistant to LPS-induced endotoxemia and CLP-induced septic shock." (PMID 36619743, 2022). "Finally, we identified and verified 9 key genes (Cd274, Cxcl1, Cxcl9, Icam1, Ifit2, Isg15, Stat1, Tlr2, and Usp18), and we predicted seven potential drugs for multi-organ damage in LPS-induced endotoxemia." (PMID 33330617, 2020). "Previous studies have demonstrated that absence of STAT1 activity exacerbates lung injury associated with endotoxemia." (PMID 30319651, 2018). "HDAC6 regulates LPS-induced iNOS expression in macrophages by modulating STAT1 activation and IRF-1 expression, and facilitates iNOS expression in the tissues during endotoxemia." (PMID 32973784, 2020).
lupus nephritis (13 papers, 2009 to 2025). Glomerulonephritis in the context of systemic lupus erythematosus. "The expression levels of miR-145, a suppressor of STAT1, are decreased in T cells from SLE patients, and increased levels of STAT1 in human SLE T cells are associated with lupus nephritis." (PMID 29868033, 2018). "These pathways are activated by key regulators such as IRF3, IRF7, and STAT1, which promote immune cell infiltration and contribute to organ damage, as seen in lupus nephritis inflammation." (PMID 39844998, 2025). "Elevated expression of STAT1 mRNA was reported in lupus nephritis and correlated with disease progression." (PMID 38474381, 2024). "It is in line with the previous finding that blockade of STAT1 activity reduces macrophage infiltration and improves renal function in mice with lupus nephritis." (PMID 29643988, 2018). "In mice with lupus nephritis (an inflammatory kidney disease), STAT1 becomes activated and blockade of STAT1 activity reduces macrophage infiltration and improves renal function." (PMID 26678048, 2015). "In addition, inhibition of the JAK2/STAT1 pathway in lupus nephritis mice can alleviate renal function damage and immune complex deposition and reduce the level of proteinuria and anti‐dsDNA IgG." (PMID 35875970, 2022). "Through this study, we concluded that OSM is associated with TIL in lupus nephritis, which may be connected with the activation of STAT3 rather than that of STAT1." (PMID 28626343, 2017). "Thus, we concluded that OSM is associated with TIL in lupus nephritis, which may be connected with the activation of STAT3 rather than that of STAT1." (PMID 28626343, 2017).
lymphopenia (13 papers, 2014 to 2025). Reduction in the number of lymphocytes. "Levels of total STAT1 (t-STAT1) were associated with the degree of lymphopenia and IL-7 serum levels in HIV-infected patients." (PMID 24603698, 2014). "In patients with HIV infection, the relatively weak association observed between IL-7 and levels of t-STAT1 suggests that lymphopenia in combination with other factors potentially driven by ongoing viral replication may play a role." (PMID 24603698, 2014). "Total WBC counts were impacted during HAZV infection, with profound leukopenia due to lymphopenia observed starting on day 3 p.i., similar to that observed in STAT1−/− mice infected with CCHFV." (PMID 41251351, 2025). "In the present study, we investigated T cell apoptosis in STAT1-GOF patients and the risk of lymphopenia in these patients, despite normal human thymic output." (PMID 38578354, 2024). "Since IL-7 in vitro was able to upregulate t-STAT1, we next analyzed its contribution in the setting of lymphopenia." (PMID 24603698, 2014). "In the present manuscript, we show that IL-7 in vitro or lymphopenia in vivo can upregulate the total levels of STAT1, -2 and -3, rendering CD4 T cells more sensitive to IFN-α." (PMID 24603698, 2014). "In STAT1-GOF patients, T lymphocyte apoptosis is increased, and T lymphopenia may determine higher risk of severe infections." (PMID 38578354, 2024). "In addition, STAT1 overexpression was related to reduce survival in CD4+ T cells undergoing lymphocytopenia-induced proliferation." (PMID 36142322, 2022). "Heterozygous gain of function mutations in STAT1 lead to impaired nuclear dephosphorylation of STAT1 and immune aberrations which include lymphopenia, reduced responses to mitogens and antigens, hypogammaglobulinemia, as well as impaired natural killer (NK) cell function." (PMID 31362757, 2019). "Recently, it was reported that overexpression of STAT1 in T cells inhibits their expansion in lymphopenic mice, which led to the suggestion of targeting STAT1 to enhance T-cell numbers in clinical settings of lymphopenia like bone marrow transplantation and HIV infection." (PMID 30796216, 2019). "We next evaluated the contributions of in vivo lymphopenia (CD4 T cell counts) and serum levels of IL-7 to t-STAT1 expression and activation (p-STAT1) in patients with chronic HIV infection." (PMID 24603698, 2014). "Taken together, these results indicate that, in the setting of HIV infection, CD4 T cell lymphopenia can contribute to upregulating t-STAT1 expression in CD4 T cells and this subsequently leads to increased levels of p-STAT1 following exposure to IFN-α." (PMID 24603698, 2014). "In the STAT1-GOF syndrome, lymphopenia has been variably reported." (PMID 38578354, 2024). "Furthermore, in the presence of lymphopenia, IL-7 not only leads to the IL-7-dependent activation of STAT1 and STAT5 but also enhances the T cell response to IFN by regulating STAT1 protein expression levels." (PMID 38675377, 2024). "Additionally, IL-7 not only leads to IL-7-dependent activation of STAT1 and STAT5 in the presence of lymphopenia, but also enhances T cell response to type-I IFN by regulating STAT1 protein expression level." (PMID 36142322, 2022). "In patients with STAT1-GOF mutations, lymphopenia represents a negative prognostic factor because it may cause higher risk of infections, also sustained by opportunistic pathogens." (PMID 38578354, 2024). "Although we could not identify a specific mechanism linking lymphopenia to apoptosis, our results may suggest that the use of a JAK/STAT inhibitor may control the signaling unbalance in the STAT1-GOF disorder and revert the increased T cell apoptosis." (PMID 38578354, 2024).
endometrial cancer (12 papers, 2016 to 2025). Primary or metastatic malignant neoplasm involving the endometrium (mucous membrane that lines the endometrial cavity). "This is in general agreement with our study, in which mutated STAT1 in endometrial cancer was negatively correlated with NK cells." (PMID 35244291, 2022). "Signal transducer and activator of transcription (STAT1)-induced upregulation of the lncRNA LINC01123 is associated with poor prognosis and promotes endometrial cancer progression." (PMID 37225681, 2023). "High LINC01123 expression is associated with advanced clinical progression and poor clinical outcomes in patients with endometrial cancer, demonstrating that STAT1 promotes proliferation and metastasis in endometrial cancer." (PMID 35244291, 2022). "Nevertheless, our data demonstrated that immune cell recruitment due to activation of STAT1 signaling axis contributes to a favorable prognosis for endometrial cancer and that Cluster IV tumors are potential candidates for immune checkpoint inhibitor therapy." (PMID 30847026, 2019). "Similar to the results reported previously in endometrial cancer cells, our study demonstrated that the elevation of STAT1 expression promotes while its knockdown inhibits EOC cell proliferation, migration, and invasion." (PMID 29751820, 2018). "For example, increased STAT1 activity in therapy-resistant endometrial cancers correlates with increased PD-L1 expression levels." (PMID 28276425, 2017). "In endometrial carcinoma (z score = 2.07, p = 0.0383), a higher CTL level indicated a better prognosis when STAT1 had relatively low expression." (PMID 36968603, 2023). "Recently, it has been reported that IFN-γ can lead to EMT transition in pancreatic cells or endometrial cancer cells through the stimulation of MUC4 transcription, which is expressed in an aggressive or metastatic tumor phenotype by the activation of STAT1." (PMID 35283421, 2022).
heart failure (12 papers, 2017 to 2026). Inability of the heart to pump blood at an adequate rate to meet tissue metabolic requirements. "Signal transducer and activator of transcription 1 (STAT1) is a member of the STAT family, and it has been proposed that STAT1 promotes the generation of larger infarcts, which can lead to heart failure, by enhancing apoptosis and negatively regulating autophagy." (PMID 37372424, 2023). "Furthermore, mice with the SCN5A N1325S mutation in the heart (TG-NS mice) exhibited the phenotype of dilated cardiomyopathy and heart failure, and other studies have indicated the upregulation of STAT1 in the hearts of TG-NS mice." (PMID 37372424, 2023). "Previous studies showed that STAT1 expression was increased in DOX-induced rat cardiomyocytes, and inhibition of STAT1 gene expression or JAK2/STAT1 signaling pathway reduced DOX-induced ferroptosis and myocardial fibrosis in rat cardiomyocytes, thereby alleviating heart failure." (PMID 39243097, 2024). "Our study found that TNIP3 serves as a novel suppressor of pathological cardiac hypertrophy by promoting STAT1 stability, which suggests that TNIP3 could be a promising therapeutic target of pathological cardiac hypertrophy and heart failure." (PMID 38926347, 2024).
Insulin resistance (12 papers, 2017 to 2024). Increased resistance towards insulin, that is, diminished effectiveness of insulin in reducing blood glucose levels. "It has been reported that IFN-γ upregulation and JAK/STAT1 pathway activation contribute to adipocyte dysfunction and insulin resistance." (PMID 37110462, 2023). "IFN-γ has been reported to induce insulin resistance by activating STAT1 in adipocytes, decreasing the phosphorylation of the serine/threonine kinase, and downregulating insulin receptor substrate 1 and glucose transporter type 4." (PMID 37110462, 2023). "Signal transducer and activator of transcription 1 (STAT1), a downstream transcription factor of IFN-γ signaling, plays a key role in the control development of adipocytes and the ability of interferon to induce insulin resistance." (PMID 34489979, 2021). "High insulin in insulin resistance may inhibit the ability of interferon alfa to block HCV replication due to the activation of PI3K by insulin, thus leading to inhibition of STAT-1, which is involved in the interferon alfa pathway." (PMID 28981513, 2017). "In addition, adipocyte-derived exosomal miR-155 targets adipose tissue-resident macrophages, promotes signal transducer and activator of transcription 1 (STAT1) signaling, and suppresses STAT6 signaling, resulting in M1 macrophage polarization and subsequent insulin resistance." (PMID 39872218, 2024).
oral cancer (12 papers, 2018 to 2025). "In conclusion, hesperidin exerted anticancer effects against oral cancer cells through the suppression of PD-L1 expression via inactivation of the STAT1 and STAT3 signaling molecules." (PMID 34500779, 2021). "Indoleamine 2,3-dioxygenase, an immunomodulatory protein, is suppressed by EGCG via blocking of gamma-interferon-induced JAK-PKC-delta-STAT1 signaling in human oral cancer cells." (PMID 34539403, 2021). "In addition to our results, EGCG was previously shown to suppress indoleamine 2,3-dioxygenase (IDO), which can enhance immune escape by blocking the IFN-γ–induced JAK/PKC/STAT1 signaling pathway in oral cancer cells." (PMID 30126206, 2018). "Hesperidin inhibited PD-L1 expression by inactivating the STAT1 and STAT3 signaling molecules in oral cancer cells." (PMID 37446814, 2023). "And in IFN-γ-stimulated human oral cancer cells, p-JAK1 and p-JAK2 are inhibited by EGCG, and EGCG inhibits STAT1 translocation to the nucleus." (PMID 34539403, 2021). "To further validate the importance of STAT1 in this process, we performed T cell killing assays with mouse oral cancer (MOC1) cells lacking STAT1." (PMID 38231444, 2024). "Otherwise, an additional investigation into enhanced tumor immunity, which leads to the inhibition of immune evasion and cancer aggressiveness, by suppressing the up-regulated expression of PD-L1 via the reduced activation of STAT1/STAT3 signaling, is worth pursuing in oral cancer cell lines." (PMID 34500779, 2021). "To enhance our understanding of STAT1 activation and regulation in HNSCC initiation, growth and anti-tumour immune responses, we determined the effects of STAT1 small interfering RNA (siRNA) knockdown on the human papillomavirus (HPV)-negative oral cancer cell lines CAL27 and UM-SCC22A." (PMID 35595823, 2022). "Since STAT1/STAT3 signaling is regarded as one of the critical pathways for cell proliferation, migration, and invasion, it is likely that the anticancer effects of hesperidin are mediated by STAT1/STAT3 signaling and activated by treatment with IFN-γ in the oral cancer cell lines." (PMID 34500779, 2021).
SARS-CoV infection (12 papers, 2010 to 2025). "STAT1-deficient mice suffer worse disease upon SARS-CoV infection with greater systemic infection and viral burden in the lungs." (PMID 23029269, 2012). "The loss of STAT1 in other cells of the knockout mouse may contribute as we have described here, to loss of wound healing control and induction of fibrosis, leading to the development of the lethal disease state after SARS-CoV infection." (PMID 20386712, 2010). "A role for AAM differentiation in immune-pathology has been elegantly verified in SARS-CoV infection using STAT6- and STAT1-deficient animals." (PMID 40854598, 2025). "With SARS-CoV infection, STAT1 plays an important role in protecting the host from severe sickness independent of IFN receptor-mediated signaling." (PMID 37052505, 2023). "SARS-CoV infection have been shown to suppress the type-I IFNs by impairing signal transducer and activator of transcription 1 (STAT1), antagonizing IFN." (PMID 35730047, 2022). "It was reported that SARS ORF6 antagonizes STAT1 function by preventing its translocation to the nucleus and acts as an interferon antagonist in the context of SARS-CoV infection." (PMID 32736569, 2020). "STAT1 phosphorylation and IRG transcription invokes a cellular antiviral state where STAT1 has been previously reported up-regulated during SARS-CoV infection." (PMID 23029269, 2012). "Specifically, we tested the role of type I, type II, and type III IFN and STAT1 in protection from SARS-CoV infection." (PMID 20386712, 2010). "The observation of a reverse correlation of IFN-β and IL-8 mRNA levels with age after SARS-CoV infection may reflect a physiological cross-regulation between antiviral STAT-1 and proinflammatory NF-κB pathways." (PMID 20140198, 2010). "In SARS-CoV infection, the ORF6 of SARS-CoV can block STAT1 translocation into the nucleus, leading to the development of the disease state." (PMID 33242255, 2020). "STAT1 and JAK1 were indeed significantly upregulated in ferret lungs only during acute SARS-CoV infection." (PMID 23029269, 2012). "Taken together, these data suggest that a STAT1-dependent, IFN type I and II receptor-independent pathway plays a key role in regulating viral clearance and survival following SARS-CoV infection." (PMID 20386712, 2010). "We infected STAT1−/− mice to evaluate whether the absence of a downstream IFN signaling protein results in increased susceptibility to SARS-CoV infection, and to determine the course of infection and pathologic changes associated with the virulent mouse-adapted virus." (PMID 20386712, 2010). "al. also demonstrated that STAT1, a key modulator of IFN α/β, λ, γ signaling, was required for the resolution of wildtype SARS-CoV infection, once again indicating the importance of the innate response in the clearance of SARS-CoV." (PMID 20386712, 2010). "STAT1 and JAK1, key upstream mediators of integrated IRG gene expression upon phosphorylation, were significantly upregulated in ferret lungs only during acute SARS-CoV infection." (PMID 23029269, 2012).